GC (GC vitamin D binding protein)
Diseases named in the same sentence as GC in open-access papers (continued):
Sharing a sentence is not in itself a finding about the gene and the disease.
infection (64 papers, 2010 to 2026). The state of being infected such as from the introduction of a foreign agent such as serum, vaccine, antigenic substance or organism. "The results show that polymorphisms in the vitamin D binding protein encoded by the GC gene are related to the infection severity (p = 0.005)." (PMID 34675344, 2021). "The kinase activity of UL13 and US3 was found to be important for the viral glycoproteins gC and gD to be modified and expressed late during infection, as loss of both UL13 and US3 diminished virion release, showing a role for UL13 in assembly and egress of the virion." (PMID 33374862, 2020). "Western blot analysis demonstrated the expression of HSV-1 proteins corresponding to distinct kinetic phases—ICP4 (immediate-early) and gC (late)—in differentiated neurons at 24 hpi and 48 hpi, showing a clear dependence on viral dose and infection time." (PMID 41596294, 2026). "The higher ICAM1 protein level at the plasma membrane of keratinocytes facilitates lymphocyte function-associated antigen 1-dependent T cell adhesion and expression of gC during infection increases VZV spread to peripheral blood mononuclear cells." (PMID 38909022, 2024). "Since VZV gC is expressed with late kinetics, its function would occur late during infection, at a time when virions are already being produced." (PMID 38909022, 2024). "To investigate the relevance of the IFN-γ-mediated ICAM1 upregulation in the context of infection and to address the role of gC, we employed two recombinant, BAC-derived VZV pOka viruses: pOka-gC-GFP and pOka-ΔgC-GFP." (PMID 38909022, 2024). "We also observed more efficient VZV spread from epithelial HaCaT cells to Jurkat cells and to peripheral blood mononuclear cells (PBMCs) when gC was expressed during infection." (PMID 38909022, 2024). "Next, immunofluorescence assays using an anti-gC antibody were performed to determine the infection rate." (PMID 37317179, 2023). "CNOT1 or CNOT3 depletion did not measurably impact the accumulation of VACV proteins, detected using a pan‐VACV antibody, or the accumulation of IE, early and late HSV‐1 proteins ICP4, US3, or gC following a low multiplicity infection." (PMID 37846490, 2023). "The humoral immune response elicited against CCHFV-M during natural infection is specific for GC and GP3834,35." (PMID 37210392, 2023). "We found that the HSV-1 immediate early protein ICP4, the early protein UL42, and the true-late glycoprotein gC were robustly expressed at 18 h post-infection (hpi) and remained constant at the highest viral doses tested." (PMID 37317179, 2023). "At 24 and 36 h after infection, a gC-specific band was detected in virus-infected cells, which was enhanced when treated with iCRT14." (PMID 35216447, 2022). "In contrast to Cohort 1 VAX, peak titers in the vaccinated group of Cohort 2 (Cohort 2 VAX) were observed at 12 weeks post-infection (433,067 ± 620,472), following a single dose of α-GC+KEX1." (PMID 36561749, 2022). "Despite diminished CD4+ T cell capacity at 8 and 14 weeks post-infection, α-GC+KEX1 elicited robust titers in both animals." (PMID 36561749, 2022). "A similar spatial expression was observed for late stage U2OS cells, with redistribution of gC from juxtanuclear sites to the periphery likely representing progressively later stages of infection." (PMID 35797345, 2022). "Future studies in our laboratory are directed at understanding the conserved and divergent functions of gC proteins in the context of natural infection to better understand the evolution of host specificity and disease pathogeneses." (PMID 34452285, 2021). "Without ACV treatment, mRNA levels of the ICP4, ICP27, ICP8, and gC genes were reduced significantly in the knockout cells compared to the control line following infection with 7134." (PMID 33563816, 2021). "Together, the results suggest that gC contributes to initial infection of cells that support a low-pH entry pathway but is not by itself a viral determinant of pathway selection." (PMID 32024702, 2020).
infection (continued). "When they assessed for infectious virus after infection in a low-pH environment, gC-null HSV-1 was lagging in intracellular transport or release from intracellular vesicles formed after endocytic entry." (PMID 33374862, 2020). "The extracts directly inhibit extracellular virions or viral attachment to the host cell as well as inhibiting the expression of ICP4, ICP8 and gC when added at various times post-infection." (PMID 33144625, 2020). "Although the intranasal anti-gC response started slower after Ab4ΔORF1/71 infection, it was compensated by a higher magnitude than the anti-gC response induced by Ab4 on days 14 and 16pi." (PMID 30440016, 2018). "We propose that VZV gC activity increases the chemokine-mediated attraction of leukocytes to the site of infection improving dissemination of the virus within the host." (PMID 28542541, 2017). "We propose that VZV gC activity facilitates the recruitment and subsequent infection of leukocytes and thereby enhances VZV systemic dissemination in humans." (PMID 28542541, 2017). "The proportion of infected LCs is quite similar to that quantified by flow cytometry in LCs emigrating onto substrate after infection of the explant (28%) with monoclonal antibody targeting HSV glycoprotein C (gC)." (PMID 25875649, 2015). "We hypothesize that Mardivirus gC plays two significant roles during transmission, one in attachment to cells and the second in binding immune molecules during natural infection." (PMID 40559546, 2025). "gC was significantly upregulated by 12 h, and both gC and gL peaked at 48 h post-infection." (PMID 39195802, 2024). "The late protein gC serves as a robust marker of the late stages of infection." (PMID 38786010, 2024). "Additionally, our investigation of BoAHV1 infection dynamics within host cells revealed early upregulation of gB, which is critical for sustained infection, while the expression of gC and gD showed variations compared to previous studies." (PMID 39195802, 2024). "Subsequently, at 4 and 6 h post-infection, the expression of gC and gL, respectively, was detected." (PMID 39195802, 2024). "The UL30 gene encoding the catalytic subunit of the viral DNA Polymerase and the ICP8 protein encoding the DNA-binding protein participates in the replication of the HSV-2 in the cell, only after which the late infection phase proteins gC (UL44 gene) and gB are produced." (PMID 37766164, 2023). "A more comprehensive study has recently been carried out using a recombinant form of HSV-1, known as the “timestamp” reporter virus, expressing fluorescent chimeras of the early protein ICP0 and the late protein gC to distinguish between early and late stages of infection." (PMID 35797345, 2022). "Further experiments determining whether avian gC proteins bind and inhibit C3 is warranted to address these differences and the potential role gC and complement may play during natural infection in the host." (PMID 34452285, 2021). "At a later stage of infection, additional fluorescence signal from gC-mCherry appears." (PMID 33380421, 2021). "Binding of gC to heparan sulfate is not strictly essential for infection since gC-deficient virus can still enter cells, although about 10-times less efficiently." (PMID 32575422, 2020). "Here, we demonstrate that gC regulates cell entry and infection by a low-pH pathway." (PMID 32024702, 2020). "By contrast, surface glycoprotein gC is expressed later in infection." (PMID 30717447, 2019). "Like HSV-1 and most other alphaherpesviruses, including EHV-1, efficient infection is initiated by a relatively unstable attachment to heparan sulfate molecules on the proteoglycan cell surface, mediated by gC and gB, followed by binding of gD to one of the specific receptors on the cell surface." (PMID 31849857, 2019). "The gB and gC signals were steadily present throughout the course of infection." (PMID 30651370, 2019). "The late gC protein signal was detected at 6 hpi and increased as infection progressed." (PMID 30651370, 2019).
infection (continued). "Since VZV gC is expressed with true late kinetics, when infectious viral particles are produced, gC may facilitate the recruitment and infection of leukocytes and optimize virus dissemination within the infected individual." (PMID 28542541, 2017). "A previous report suggested that for neutralization of herpes viridae anti-gC antibodies are particularly important whereas at the same time antibody titers against gC (ORF14) have been reported to be lower in vaccinees compared to children after wild type infection." (PMID 24204928, 2013). "Thus, the role of gC proteins during natural infection is likely a complex mechanism, where gC may play multiple roles." (PMID 40559546, 2025). "Additionally, gC can regulate cell entry and infection by a low-pH pathway." (PMID 33374862, 2020). "In addition, anti-gC IgG6 antibodies were induced at very low values after infection." (PMID 30440016, 2018). "At a multiplicity of infection (MOI) of 3 for 18 h, nearly all cells (>90%) displayed strong gC immunoreactivity." (PMID 41596294, 2026). "The presence of ICP34.5 in KO cells prior to infection successfully reduced the phosphorylation of eIF2α and PKR, resulting in higher expression of the viral protein gC." (PMID 40198737, 2025). "To investigate how oHSV promotes NETosis, we found that oHSV infection increased IGF2BP3 and MIB1 expression while suppressing FTO in a time-dependent manner, along with the detection of viral proteins ICP0, ICP8, and gC." (PMID 38167409, 2024). "Infection by HSV-1 is facilitated through viral surface glycoproteins, gC, gB, gD, gH and gL, which are present in the viral envelope." (PMID 33144625, 2020). "DEV UL54 continuously promoted the viral mRNA expression of UL30 and gC, and an increase was observed for UL48 and gD, except in the early stage of infection." (PMID 28432334, 2017). "For chicken herpesviruses, MDV, and GaAHV3 (strain 301B/1 strain), gC is not essential for in vitro propagation but is required for horizontal transmission or natural infection in chickens." (PMID 40559546, 2025). "Although gC is not essential for in vitro propagation, it is essential for horizontal transmission or natural infection of MDV and GaAHV3 (301B/1 strain) in chickens and HSV-1 and VZV replication in human skin cells." (PMID 38793663, 2024). "gC is a true late protein, as its transcription occurs at very late during VZV infection probably due to the lack of the factors required for gC synthesis during early phases of infection." (PMID 36630443, 2023). "Absence of gC results in reduced binding of virus to cells, although the virus that binds can enter cells and initiate infection." (PMID 33374862, 2020). "Our results show that recombinant soluble VZV gC ectodomain (rSgC) binds chemokines and potentiates chemokine-dependent leukocyte migration, including that of human tonsillar leukocytes, the target of VZV during primary infection." (PMID 28542541, 2017). "Following infection of mES cells, we examined the extent of HSV-1 gene expression using antibodies against HSV-1 ICP27, ICP8 and glycoprotein C (gC), which are immediate-early (IE), early (E) and late (L) gene products, respectively, using immunofluorescent microscopy." (PMID 22815272, 2012). "From the data accumulated from both the ear pinna and whisker pad infection models that target DRG and TG, respectively, we conclude that as for the TK and gC promoters expression of Cre-recombinase from the L1 VP16P is largely incompatible with cell survival and latency establishment." (PMID 21752961, 2011). "That is, HSV-1 gC is not spliced and the full-length protein (gC1) is largely produced during infection when ICP27 is normally present, while non-functional ICP27 mutants lead to splicing UL44 (gC) mRNA to produce a secreted form of gC, which they refer to as SEgC." (PMID 38793663, 2024).
infection (continued). "ICP22 and TK transcripts were significantly more abundant in HSV1 vhs-GFP infection compared to WT, but the level of the late gC transcript was not significantly different between the two viruses, which was in agreement with our previous results on Δvhs infected cells." (PMID 35758691, 2022). "However, this conclusion does not exclude the role of gB, together with gC, to bind cell surface heparan sulfate and help the attachment of virions to cells during the initial events of infection." (PMID 25654240, 2015). "Thus, gC retargeting favors infection of target cells but does not prevent off-target infection." (PMID 30799657, 2018). "Ammonium chloride inhibited infection of polarized HaCaT cultures by both HSV-1 ∆gC and gCR, suggesting that gC is not required for the pH-dependence of entry from basolateral surfaces." (PMID 40270821, 2025). "It was reported that following infection VZV glycoprotein C (gC) was not expressed in most infected neurons and gC expression was markedly reduced in a minority of VZV-infected neurons whereas expression of the early–late VZV gE glycoprotein was abundant." (PMID 33804210, 2021). "qRT-PCR for the IE ICP27 transcript and the L gC transcript showed that, as expected, transcription of ICP27 occurred but was reduced while transcription of gC was blocked in the presence of CHX and hence the absence of ongoing infection (right-hand panel)." (PMID 30475899, 2018).
cancer (50 papers, 2009 to 2025). A tumor composed of atypical neoplastic, often pleomorphic cells that invade other tissues. "Associations between vitamin D biochemical status and cancer may be modified by vitamin D binding protein isoforms which are encoded by GC (group-specific component)." (PMID 39705237, 2024). "In this study, we propose that GC protein, mainly derived from local cancer cells, promotes PNI in PDAC independently of vitamin D transport." (PMID 40923379, 2025). "Collectively, these data demonstrate that GC protein engages integrin receptor signaling to display distinct functions in cancer cells and Schwann cells, thus enabling PNI." (PMID 40923379, 2025). "A specific form of VDBP, GC, has been suggested to improve cancer survival among both men and women in the US." (PMID 40732958, 2025). "We combined the decrease in gC-mediated virus attachment to off-tumor tissues via GAGs with the specific retargeting to cancer receptors intrinsic to ReHV technology." (PMID 38539478, 2024). "Vitamin D-binding protein (GC) facilitates the immune system response against cancer cells by proper activation of macrophages (Gc-MAF), leading to their phagocytosis." (PMID 37900279, 2023). "Acting as a ligand for the ITGB1 receptor, GC protein can directly influence cancer cells, enhancing their invasive capabilities toward nerves, promoting dedifferentiation of Schwann cells, and increasing the bidirectional chemoattractant between cancer cells and Schwann cells." (PMID 40923379, 2025). "The cancer stemness-related gene, CD133, was overexpressed in the case of gP, gC, gO, and gPC treatment combinations." (PMID 35651701, 2022). "Importantly, these experiments also demonstrated that HSV1-dICP0 viral mRNAs (ICP4, gC, TK) are highly transcribed and more abundant in polysome fractions when 4T1 or NT2196 cancer cells were treated with asTORi as compared to DMSO control." (PMID 30138450, 2018). "As results of initial validation by western blotting in relatively advanced cases and further validation including the less advanced cases by western blotting, the expression levels of the four proteins ApoA-IV, GC, RBP4, and CLEC3B were greater in cancer patients than in controls." (PMID 22091389, 2011). "Within the VitD pathway, the VitD binding protein (VDBP also known as GC) was significantly reduced in OSCC samples, suggesting an impairment in the transport of VitD from the skin to circulation as previously reported, which suggest that this metabolite is more concentrated in cancer samples." (PMID 34025655, 2021). "Therefore, genetic variation in GC may alternatively influence cancer outcome via GcMAF, a biological mechanism independent of vitamin D levels." (PMID 29409465, 2018).
tumor (34 papers, 1997 to 2025). "In the multivariate model, VDBP (GC) AC/CC genotype and BL 25-VD were predictors of this cut-off value, associated with tumor progression." (PMID 30669662, 2019). "The correlation analysis between glycosylation enzymes and glycans in PDAC tumor samples revealed two coherent regulatory patterns, labeled GC.1 (red) and GC.2 (blue)." (PMID 41093273, 2025). "GC protein was significantly downregulated by AAV‐mediated shRNA in the tumor tissues of KPC mice, as evidenced by immunohistochemical analysis." (PMID 40923379, 2025). "The vitamin D binding protein, the GC protein, is a multifunctional protein that binds circulating vitamin D and also increases macrophage killing of tumor cells." (PMID 38410461, 2024). "Meanwhile, the hub genes from the DEGs between T and LM groups (ALB, FGG, AHSG, TF, and GC) also showed marked alterations in the correlations, indicating potential mechanisms involved in the tumor metastasis." (PMID 32496505, 2020). "Herein, we demonstrated that the interaction between NKDCs and NKT cells was required for optimal anti-tumor immunity mediated by α-GC." (PMID 23878807, 2013). "Labelled by benign signatures, subclusters 1 and 2 similarly overexpressed metabolism‐related genes and tumour suppressors (KLF6, EGR1, GC, FAM46A, ZFP36, BTG2, etc.)." (PMID 35075805, 2022). "In vivo imaging experiments were performed by intravenous injection of the GCR and GC proteins into U87MG and CHO tumor-bearing mice." (PMID 25654118, 2015).
metabolic disorders (5 papers, 2020 to 2024). "Regarding a VD deficiency, the genes LIPC, HAL, GC and the Cytochrome P450 Family genes were among those which are more strongly associated with nutritional/metabolic diseases." (PMID 36430729, 2022). "Importantly, the LIPC gene was more prominently associated with nutritional/metabolic diseases, with the genes GC, HAL and the Cytochrome P450 Family also being implicated." (PMID 36430729, 2022).
GC also shares sentences with these, for which no sentence is quoted: Obesity (15 papers); multiple sclerosis (14); osteoporosis (13); Insulin resistance (11); gestational diabetes mellitus (10); lung carcinoma (10); type 2 diabetes mellitus (9); chronic obstructive pulmonary disease (8); diabetic nephropathy (8); liver diseases (8); rheumatoid arthritis (8); coronary artery disease (7); endometriosis (7); prostate carcinoma (7); type 1 diabetes (7); hypovitaminosis D (6); kidney disease (6); nephrotic syndrome (6); polycystic ovary syndrome (6); preeclampsia (6); tuberculosis (6); Alzheimer disease (5); bladder cancer (5); chronic kidney disease (5); hepatocellular carcinoma (5); Hyperglycemia (5); liver cirrhosis (5); Nephropathy (5); ovarian carcinoma (5); bipolar disorder (4).
A further 197 diseases each share a sentence with GC in 4 papers or fewer.